AMER2 (APC membrane recruitment protein 2)
Description:
Negative regulator of the canonical Wnt signaling pathway involved in neuroectodermal patterning. Acts by specifically binding phosphatidylinositol 4,5-bisphosphate (PtdIns(4,5)P2), translocating to the cell membrane and interacting with key regulators of the canonical Wnt signaling pathway, such as components of the beta-catenin destruction complex.
Synonyms: FAM123A; FLJ25477
Tractability: Antibody: UniProt places it where antibodies can reach, with high confidence; its Gene Ontology location is reachable by antibodies, with high confidence; the Human Protein Atlas places it where antibodies can reach. PROTAC: its protein half-life has been measured.
Gene: Protein-coding gene on chromosome 13 (25,161,679 to 25,172,288, reverse strand). Ensembl gene ENSG00000165566.
Subcellular location: Cell membrane
Subcellular location (Human Protein Atlas): Plasma membrane
Gene Ontology:
Molecular function: phosphatidylinositol-4,5-bisphosphate binding; protein binding; beta-catenin binding
Biological process: negative regulation of canonical Wnt signaling pathway; ectoderm development; regulation of canonical Wnt signaling pathway
Cellular component: plasma membrane
Genetic constraint (gnomAD): Loss-of-function variants: 1 observed, 7.24 expected, observed/expected ratio (o/e) 0.14, 90% interval 0.048 to 0.65. That is too few expected variants to judge how well the gene tolerates losing a copy. Missense variants: 988 observed, 894.75 expected, observed/expected ratio (o/e) 1.1, 90% interval 1.05 to 1.16. Synonymous variants: 485 observed, 403.2 expected, observed/expected ratio (o/e) 1.2, 90% interval 1.12 to 1.3.
Homologues: Orthologues: chimpanzee AMER2 (82% identical), macaque AMER2 (80% identical), mouse Amer2 (79% identical), rat Amer2 (72% identical), rabbit AMER2 (65% identical), pig AMER2 (62% identical), dog AMER2 (57% identical), guinea pig AMER2 (50% identical), tropical clawed frog amer2 (39% identical), zebrafish amer2 (32% identical). Paralogues in human: AMER1 (24% identical), AMER3 (16% identical).
Diseases named in the same sentence as AMER2 in open-access papers:
AMER2 is named in the same sentence as 5 diseases in open-access papers, as found by Europe PMC text mining. Sharing a sentence is not in itself a finding about the gene and the disease. The quoted sentences say what the papers report.
colorectal cancer (2 papers, 2017 to 2022). A primary or metastatic malignant neoplasm that affects the colon or rectum. "FAM123A, also known as AMER2, is associated with microtubule proteins, and is a paralog of the well-documented FAM123B, a tumor-suppressor whose loss-of-function by mutation, methylation and copy-number aberrations is known to play a pivotal role in colorectal cancer, especially in older patients." (PMID 35202405, 2022).
cancer (3 papers, 2011 to 2023). A tumor composed of atypical neoplastic, often pleomorphic cells that invade other tissues. "AMER2 has been previously shown to be associated with microtubule stability and as a negative regulator of Wnt-pathway but its role in other cancers and EWS is currently not known." (PMID 37122563, 2023). "We observed that relative to other cancer types, protein expression of GPR64, UGT3A2 and AMER2 is typically enhanced in EWS cancer cells." (PMID 37122563, 2023).
AMER2 also shares sentences with these, for which no sentence is quoted: tumor (3 papers); gastric carcinoma (1); pancreatic cancer (1).